MEN1 (menin 1)
Diseases named in the same sentence as MEN1 in open-access papers (continued):
Sharing a sentence is not in itself a finding about the gene and the disease.
breast cancer (continued). "This is exemplified by the analysis of the breast cancer dataset, from which the well-known but rarely mutated cancer genes CDKN1B (7 mutations out of 772 samples), KRAS (6 mutations) and MEN1 (5 mutations) were identified." (PMID 25903787, 2015). "In this regard, there are several possible mechanisms of involvement for MEN1 in breast cancer formation." (PMID 24959251, 2014). "Further researches of MEN1 gene and menin protein may contribute to the therapeutic strategies of breast cancer." (PMID 40994809, 2025). "This aligns with international studies, which found no significant increase in breast cancer risk among MEN1 patients in the U.S. and Tasmania, despite a higher relative risk in Dutch patients." (PMID 40607214, 2025). "Interestingly, 11 patients had multiple neoplasms; in addition to those with MEN1 and neurofibromatosis, there were 4 breast carcinomas, 3 colon adenocarcinomas, 2 prostate carcinomas, and one myeloma." (PMID 40553402, 2025). "This could potentially explain the observed increased risk of breast cancer in patients with PHPT, even after excluding studies focusing on patients with MEN1." (PMID 38772934, 2024). "Various non-endocrine tumors associated with MEN1 have been reported, including facial angiofibroma, lipoma, meningioma, leiomyoma, and breast cancer, but only one case of MEN1 with LGFMS has been reported." (PMID 38200366, 2024). "MEN1 may bring with other tumors, including adrenal tumor, gastric tumor, skin tumor, subcutaneous tumor, and recently reported breast cancer." (PMID 37795364, 2023). "We further evaluated the significance of MEN1 expression in survival of the breast cancer patients." (PMID 37437063, 2023). "While the molecular functions of MEN1 are being widely explored in previous researches, we aimed to evaluate the MEN1 gene expression pattern and determine its relevance to clinical parameters in 142 sporadic breast cancer patients." (PMID 37437063, 2023). "Clinical details of 21 cases of breast cancer in women with genetically confirmed MEN1." (PMID 36325452, 2022). "Third, in more recent population studies, germline MEN1 variants are not clearly associated with a higher risk of breast cancer, and other publications have not reported a breast cancer risk in MEN1 patients greater than that of the general population." (PMID 36325452, 2022). "In mutation-negative, clinical MEN1 patients, the age of breast carcinoma diagnosis was not different from the general Dutch population." (PMID 36325452, 2022). "A recent case–control study found a surprisingly high prevalence of breast cancer in MEN1 patients." (PMID 34889280, 2021). "Evidence of a connection to another thyroid cancer-related syndrome (MEN1) was recently demonstrated in breast cancer, but a possible link to MEN2A is novel and, if confirmed, would represent an unusual case of a gain-of-function mutation linked to breast cancer risk." (PMID 28569218, 2017). "While the absence of an effect could reflect redundancy from another cell death inhibitor, a more likely possibility is differences in the cancer biology of MEN1 tumors in comparison to breast cancers." (PMID 26709830, 2015). "Interestingly, a lot of rarely mutated putative driver genes that were detected in breast cancer have been described as copy number amplifications (e.g. ERBB2) or deletions (e.g. RB1, MEN1, PTEN) before." (PMID 25903787, 2015). "The present study reports the case of a patient with MEN1-associated tumors and breast cancer, in which we identified germline mutations in MEN1, but not in BRCA1/2." (PMID 24959251, 2014). "Although increasing evidence for MEN1-associated non-endocrine tumors has been reported, there are limited data on the association of breast cancer with MEN1." (PMID 24959251, 2014). "However, the paradoxical role of MEN1 is reported in sporadic breast cancer cases." (PMID 37437063, 2023). "The study hypothesized that the clinical spectrum of MEN1 might include breast cancer." (PMID 24959251, 2014).
breast cancer (continued). "Our findings illustrate that germline cancer gene panel testing should be considered in specific patients with a co‐occurrence of breast cancer and NET and these panels should include MEN1 and other hereditary cancer syndrome genes." (PMID 31592449, 2019). "For example, mir-21 and TRIM33, which are both regulators involved in breast cancer, are located in an MCF7-specific cluster, whereas mir-194-2, mir-192 and MEN1 as leukemogenesis in a K562-specific cluster." (PMID 24357409, 2014). "Our findings indicate that breast cancer incidence in Korean MEN1 patients is not significantly higher." (PMID 40607214, 2025). "Although research in this field is ongoing, the role of MEN1 in the onset and progression of breast cancer is not fully known." (PMID 37437063, 2023). "The previous studies indicate the functional significance of MEN1 in regulating breast cells proliferation but its relevance in development and progression of breast cancer is still not known." (PMID 37437063, 2023). "We also report that MEN1 mutations, especially at NLS are not prominent in Indian breast cancer patients included in our study." (PMID 37437063, 2023). "In contrast, relatives without MEN1 and breast cancer had a median age of diagnosis of 57.5 years (range 40 to 85 years; p=0.03), closer to the mean age at breast cancer diagnosis (61.2 years) in the Dutch population." (PMID 36325452, 2022). "To date, there have been approximately 90 or fewer cases of breast carcinoma in women with MEN1 reported in the literature; breast cancer has not yet been reported in a man with MEN1." (PMID 36325452, 2022). "The authors also assessed exposure to radiation from computerized tomography (CT) scans done for MEN1 surveillance and the frequency of CT scans was similar for women with and without breast cancer." (PMID 36325452, 2022). "After the exclusion of the 2 MEN1 patients and their controls, however, no statistically significant increase was found in breast cancer incidence (RR 2.64 (0.63–11.04), P = 0.167)." (PMID 34374651, 2021). "The most frequent non-endocrine neoplasm in MEN1 is breast cancer, which is in the MEN1 setting characterized by earlier onset as compared to non-MEN1 patients." (PMID 33312161, 2020). "However, in our results we found that correlation of MEN1 upregulation with molecular subtype (p = 0.118) and clinical stage (p = 0.341) of breast cancer is not significant." (PMID 37437063, 2023). "ARC abundance increases in multiple human cancers, and the absence of an effect of nol3 deletion on MEN1 tumor load in this study contrasts with the amelioration of tumor growth (as well as metastasis) resulting from nol3 inactivation in a genetic mouse model of breast cancer." (PMID 26709830, 2015).
multiple endocrine neoplasia (40 papers, 2013 to 2026). Multiple endocrine neoplasia (MEN) is a group of rare inherited cancer syndromes characterized by the development of two or more endocrine gland tumors, sometimes with tumor development in other tissues or organs. "This is distinct from the MEN1 germline mutation associated with multiple endocrine neoplasia syndrome." (PMID 41293361, 2025). "Second, our study did not include tumor markers, such as CA19-9 and CEA, and clinical syndromes (e.g., multiple endocrine neoplasia syndromes) or genetic syndromes (e.g., mutations in MEN1, VHL, or other relevant genes)." (PMID 38087239, 2023). "NETs harbouring mutations in the tumour suppressor gene MEN1 (multiple endocrine neoplasia) have been suggested to be derived from ductal or acinar cells, and possibly from progenitor cells of these compartments after accumulating mutations in MEN1." (PMID 34543699, 2021). "Younger patients also had a lower rate of multiple endocrine neoplasia type-1 (MEN-1) mutation, which is associated with multiple microtumors and unfavorable outcomes." (PMID 32899271, 2020). "The mean age at presentation was 52 years; 55% were female patients, 11% were associated with MEN1 (multiple endocrine neoplasia 1) or VHL (Von Hippel–Lindau); mean tumor diameter was 3.3 cm (standard deviation, SD) (2.92)." (PMID 24403235, 2013). "Of note, Menin has been discovered as a tumor suppressor gene in a hereditary cancer predisposition syndrome “Multiple Endocrine Neoplasia” (MEN1‐syndrome) where inactivating mutations in the MEN1‐gene cause tumor development in different endocrine organs in about 80% of the gene carriers." (PMID 39887730, 2026). "MEN syndrome is an umbrella term used to describe a family of tumor syndromes ultimately characterized by histologically similar tumors arising in patients and families with mutations in one of four genes: MEN1, RET, CDKN1B, and MAX." (PMID 39336996, 2024). "The clinical syndromes (e.g., multiple endocrine neoplasia [MEN] syndromes) or genetic syndromes (e.g., mutations in MEN1, VHL, or other relevant genes) could occur in PNENs." (PMID 38087239, 2023). "In patients with multiple endocrine neoplasia type 1 (MEN1), a hereditary syndrome associated with NET occurrence, bone damage may carry other consequences." (PMID 32276412, 2020). "Furthermore, pHPT could also be the leading phenotype in patients with variable expression of multiple endocrine neoplasia due to a MEN1 mutation." (PMID 41009532, 2025). "Protein kinase mutations induce Carney Complex, whereas mutations in menin (MEN1) or cyclin-dependent kinase inhibitor 1B (p27, MEN4) cause multiple endocrine neoplasia, a genetic illness." (PMID 39812047, 2025). "Familial MM can be associated with genetic syndromes such as Neurofibromatosis type 2 (NF-2), Cowden syndrome, Multiple Endocrine Neoplasia 1 (MEN1), Werner syndrome, Rubinstein–Taybi syndrome, Gorlin syndrome, and Li–Fraumeni syndrome." (PMID 40283561, 2025). "MEN4 is a recently identified MEN syndrome that involves the same primary organs as MEN1, but is less common and tends to show a more indolent course." (PMID 39336996, 2024). "Multiple endocrine neoplasia (MEN1 and MEN2), Li–Fraumeni syndrome, hereditary diffuse gastric cancer syndrome, Peutz–Jeghers syndrome, and PTEN hamartoma tumor syndrome represent other genetic malformations that can cause SPM or MPM." (PMID 39594177, 2024). "Multiple endocrine neoplasia syndromes (MEN-syndrome) are rare complex heredity cancer syndromes (incidence rate in MEN1: 2–20/100,000 and MEN2: 1/350,000) with variable endocrine manifestation." (PMID 30817772, 2019). "Twenty-five consecutive cases of genetically proven MEN-syndrome were evaluated in our study including 10 patients with MEN1 and 15 patients with MEN2." (PMID 30817772, 2019). "Five patients were known with multiple endocrine neoplasia syndrome (three patients with MEN1 and two patients with MEN2a) and 17 patients had lithium associated disease." (PMID 31367807, 2019).
multiple endocrine neoplasia (continued). "We retrospectively evaluated 25 patients with MEN-syndrome (10 MEN1/ 15 MEN2) including 11 men and 14 women between 28–62 years of age." (PMID 30817772, 2019). "Neuroendocrine hyperplasia was seen in 40% of the cases in this subgroup, and DIPNECH was diagnosed in approximately 20% of the patients, including a patient with known MEN1 (multiple endocrine neoplasia)." (PMID 29770932, 2018). "The fourth type of multiple endocrine neoplasia is the most recently introduced and includes subjects phenotypically similar to MEN1 but not carrying any germline mutation in the the menin gene." (PMID 35355569, 2022). "Multiple endocrine neoplasia (MEN) type 1 syndrome is an autosomal dominant disorder caused by germline mutations in MEN1 gene, characterized by tumours in endocrine and nonendocrine organs." (PMID 30186640, 2018). "Multiple endocrine neoplasia (MEN1) is a rare inherited multi-tumour syndrome, affecting specific neuroendocrine organs and non-endocrine tissues with a variable spectrum of over 20 possible different combinations, caused by inactivating heterozygote mutations of the MEN1 gene." (PMID 30428914, 2018). "Human germline CDKN1B mutations are associated with approximately 2% of the cases of MEN1 mutation-negative multiple endocrine neoplasia." (PMID 28533356, 2017). "Multiple endocrine neoplasia was diagnosed in 14 patients (6 %), all MEN1." (PMID 26872616, 2016). "Multiple endocrine neoplasia (MEN) syndromes are part of a spectrum of clinically well-defined tumor syndromes ultimately characterized by histologically similar tumors arising in patients and families with mutations in one of the following four genes: MEN1, RET, CDKN1B, and MAX." (PMID 39336996, 2024). "Since the occurrence of multiple endocrine neoplasia later in life in sporadic cohorts with clinical MEN-1 show that most are genetically negative for mutations in MEN1 and CDKN1B, the cause of the coexistence of acromegaly and PHP remains unclear." (PMID 32311048, 2020). "After the identification of a novel p27 mutation (p27 p.177fs) in a rat model of MEN syndrome, Pellegata and colleagues reported the discovery of a germline nonsense mutation (p.W76*) in heterozygosis in a patient suspected for MEN1 syndrome, but negative for MEN1 mutations." (PMID 30065701, 2018). "During the analysis of the sample, specific attention was paid during WES to the genes associated with multiple endocrine neoplasia (CDKN1B, RET, MEN1) and TSC genes, but no variants clinically relevant to the described phenotype of the patient were observed." (PMID 34573383, 2021). "The analysis of the MEN-1 (Multiple Endocrine Neoplasia) gene was negative in both cases." (PMID 33936819, 2021).
acromegaly (30 papers, 2000 to 2026). Acromegaly is an acquired disorder related to excessive production of growth hormone (GH) and characterized by progressive somatic disfigurement (mainly involving the face and extremities) and systemic manifestations. "Syndromes associated with acromegaly include multiple endocrine neoplasia type 1 (MEN1) and type 4 (MEN4), Carney complex type 1 (CNC), McCune–Albright syndrome (MAS), the 3P association (3Pa), and neurofibromatosis type 1 (NF1)." (PMID 39194755, 2024). "Data on familial forms of acromegaly associated with MEN1 are very limited, with an overall prevalence rate <1% in acromegalic subjects." (PMID 37842314, 2023). "Among patients with a Ki-67 index ≥ 3%, 36.36% presented with one genetic syndrome associated with acromegaly (MEN1, McCune–Albright syndrome, or Carney syndrome), while in the group with a Ki-67 < 1%, only 6.74% did, p = 0.02." (PMID 38137536, 2023). "Therapy: First line treatment for MEN1-associated acromegaly is the same as in current acromegaly guidelines; however, patients require neurosurgery more often and multimodal approaches, especially paediatric cases." (PMID 33805450, 2021). "Among patients with isolated acromegaly, it has been shown that 1.2% of those younger than 30 years with sporadic cases can harbor a mutation in the MEN1 gene." (PMID 32311048, 2020). "Screening for MEN1 mutations in patients with acromegaly should be considered in the presence of other features of the syndrome or in the presence of a family history of MEN1." (PMID 28161730, 2017). "In addition, 1.2% of patients without clinical signs of familial history and aged under 30 with sporadic cases of acromegaly were found to have a mutation in the MEN1 gene." (PMID 39194755, 2024). "MEN1 mutations were described in 1.2% of sporadic acromegaly patients younger than 30 years of age." (PMID 28161730, 2017). "Somatotropinomas causing acromegaly occur in 3–6% of MEN1 patients." (PMID 25210615, 2014). "The association of acromegaly and Conn’s adenoma raised the hypothesis for MEN1 in our patient, therefore the parathyroid glands were investigated using ultrasound." (PMID 25210615, 2014). "Nine patients were registered as having a hereditary syndrome associated with PT (7 patients with MEN1, 1 with MEN4, and another with familial acromegaly)." (PMID 40277238, 2025). "Six cases of 3PA have been linked to germline defects in MEN1 (four cases) and the RET proto-oncogene (two cases), with one case of acromegaly associated with MEN1 and another with RET." (PMID 39194755, 2024). "Histological findings: In MEN1, 66.7% of adenomas are both GH- and prolactin-positive in immunohistochemistry, compared to isolated acromegaly (76.1%)." (PMID 39194755, 2024). "As in MEN1, acromegaly is expected to be found in 10% of MEN4 cases, whereas Cushing disease occurs in 5% of patients." (PMID 37761922, 2023). "Even though acromegaly represents an infrequent part of MEN1, with a penetrance of 10% due to its severe impact, the diagnosis of such skin findings should not be overlooked." (PMID 36428828, 2022). "Familial isolated pituitary adenoma syndrome is the most common familial cause of acromegaly/gigantism, as available data suggest that syndromic familial acromegaly, due to Carney complex, MEN1, MEN4 and SDH-related syndromes, are less common." (PMID 28161730, 2017). "We observed an association between acromegaly and genotype-negative MEN1, as seen in several prior studies." (PMID 39946193, 2025). "The age at the diagnosis of acromegaly in the course of MEN1 is around 40 years." (PMID 33805450, 2021). "Acromegaly in MEN1: One fourth of PitNETs related to MEN1 are GH-secreting tumours." (PMID 33805450, 2021). "Among all MEN1 patients, acromegaly occurs in about 10% of cases." (PMID 33805450, 2021). "Acromegaly can be part of familial diseases other than MEN1." (PMID 31823249, 2020). "In fact, only 2 of the MEN1 positive genetic tests were in patients with acromegaly." (PMID 32311048, 2020).
acromegaly (continued). "Although three patients with MEN1-associated acromegaly are reported to be treated medically, no data are available of their SRLs responsiveness." (PMID 28161730, 2017). "In MEN1 patients with acromegaly, the diagnosis is usually made after 40 years of age." (PMID 28161730, 2017). "However, without genetic studies on gene mutations (e.g., AIP, PRKAR1A, GPR101, GNAS, MEN1, CDKN1B, SDHx, MAX, it is difficult to assess whether OL-23/77 was affected by gigantism and acromegaly or just one of these diseases." (PMID 35498425, 2022). "Since there are cases of extra-pituitary GH production, it is crucial to rule out ectopic acromegaly in cases of MEN1-related acromegaly to avoid performing unnecessary pituitary surgery on a patient." (PMID 39194755, 2024). "This is consistent with a later age of onset described in a cohort of sporadic clinical MEN-1 patients with negative testing for MEN1 mutations which included all phenotypes of MEN-1, but only few with acromegaly." (PMID 32311048, 2020). "Sixteen patients with acromegaly and PHP underwent rigorous genetic testing with DNA sequence analysis performed for genes including: MEN1, CDC73, CDKN1A, CDKN1B, CDKN2B, CDKN2C, and AIP, as well as MLPA to search for deletions or duplications in MEN1, CDC73, CDKN1B, and AIP genes." (PMID 32311048, 2020). "However, given the overall rarity of MEN1-related acromegaly, this variable was not included in regression modeling." (PMID 39946193, 2025). "Many patients with acromegaly and clinical MEN-1 yield negative testing for MEN1 mutations." (PMID 32311048, 2020). "However, some other families with isolated acromegaly do not have abnormalities of the MEN1 gene, even though segregation analysis in families with isloated acromegaly and LOH studies of somatotrophinomas indicated that the gene was likely to be located on chromosome 11q13." (PMID 23933118, 2014).